ID3 (inhibitor of DNA binding 3)
Diseases named in the same sentence as ID3 in open-access papers (continued):
Sharing a sentence is not in itself a finding about the gene and the disease.
B-cell lymphomas (5 papers, 2015 to 2024). "In another cohort of B‐cell lymphoma patients, BMP7 or ID3 high also significantly associated with better survival." (PMID 38229201, 2024). "The combined expression of VPREB3 and ID3 was used to develop a new helpful tool for the routine diagnosis of mature aggressive B-cell lymphomas." (PMID 36443709, 2022).
coronary artery disease (5 papers, 2014 to 2024). "Given that CAC is a predictor of coronary disease burden, we sought to determine directly if the ID3 SNP rs11574 is associated with atheroma burden measured by IVUS and with stenosis severity by QCA in a second cohort." (PMID 24603695, 2014). "ID3 SNP rs11574 has also demonstrated a significant link to coronary artery disease for Caucasians besides a condensed range of African Americans and Hispanics." (PMID 39846697, 2024).
small cell lung carcinoma (5 papers, 2012 to 2021). Small cell lung cancer (SCLC) is a highly aggressive malignant neoplasm, accounting for 10-15% of lung cancer cases, characterized byrapid growth, and early metastasis. "Numerous studies indicated the important role of Id1 in angiogenesis, for example, in small cell lung cancer, suppressed expression of Id1 and Id3 was accompanied by decreased angiogenesis." (PMID 32410828, 2020). "Suppressing both Id1 and Id3 expression was accompanied by decreased angiogenesis and increased apoptosis and greatly reduced the average size of small cell lung cancer in nude mice." (PMID 32410828, 2020). "Silencing Id3 alone in small cell lung carcinoma can also reduce proliferation in spite of persistent Id1 expression." (PMID 23342268, 2012).
breast tumors (4 papers, 2013 to 2024). "In spontaneous primary tumors of the breast in the MMTV-Her2/neu model, genetic analyses indicated that loss of Id1 and/or Id3 was insufficient to inhibit tumor growth and needed to be combined with suboptimal doses of chemotherapy to cause regression." (PMID 34031428, 2021). "For example, different breast tumors failed to grow and/or metastasize in Id1 (+/−) Id3 (−/−) knockout mice." (PMID 23311395, 2013).
endometriosis (4 papers, 2014 to 2024). The growth of functional endometrial tissue in anatomic sites outside the uterine body. "Our time course transcriptomic analyses revealed that BMP ligands and SMAD1/5/4 transcriptional targets, ID2 and ID3, were consistently downregulated in stromal cells from individuals with endometriosis during in vitro decidualization." (PMID 38402336, 2024). "The binding level of NF-Y protein complex to the promoter regions of ID1, ID2, and ID3 genes was displayed through ChIP-Real-Time-PCR and according to the results; it was considerably increased in eutopic group of endometriosis patients in proliferative phase." (PMID 30876429, 2019). "Furthermore, the incorporation of NF-Y complex on CCAAT box region of ID1, ID2, and ID3 promoters was highly enhanced in endometriosis patients." (PMID 30876429, 2019). "Therefore, the involvement of other conserved regulatory regions and/ or other regulatory elements in the process of ID3 gene expression regulation in endometrial lesions (ectopic tissue) of endometriosis patients have a great likelihood." (PMID 30876429, 2019). "As the TATA box lacking genes are intensively dependent to their CAT box region, the role of NF-Y protein in ID2 gene regulation and epigenetic in endometriosis patients is more significant than its binding to the ID1 and ID3 genes." (PMID 30876429, 2019). "Similar to BMP2, the ID1 and ID3 genes were progressively increased over the time course treatment in the samples derived from donors without endometriosis while they were conversely downregulated in the endometriosis cohort." (PMID 38402336, 2024). "We also observed persistent downregulation of the classical BMP/SMAD1/5/4 target genes, ID2 and ID3, suggesting that impaired BMP signaling was resulting in decreased transcriptional activation by SMAD1/5/4 in stromal cells derived from individuals with endometriosis." (PMID 38402336, 2024). "However, given that SMAD4 enrichment was decreased at the ID1 and ID3 promoter regions, and this corresponds with decreased ID gene expression, it was likely that BMP signaling pathways also impair SMAD1/5/4 binding activities in the stromal cells from individuals with endometriosis." (PMID 38402336, 2024). "The canonical SMAD1/5 target genes, ID2 and ID3, were significantly decreased during days 4 and 6 of EPC treatment in the endometrial stromal cells derived from individuals with endometriosis relative to those without." (PMID 38402336, 2024).
glioblastoma (4 papers, 2017 to 2025). The most malignant astrocytic tumor (WHO grade IV). "Western blotting showed that CD133, ALDH1, NANOG, ID1 and ID3 were downregulated in U251 and T98G glioblastoma cells upon ONC201 treatment at 72 h." (PMID 28767654, 2017).
Immunodeficiency (4 papers, 2009 to 2022). Failure of the immune system to protect the body adequately from infection, due to the absence or insufficiency of some component process or substance. "Recent next-generation sequencing studies on the pathogenesis of BL have revealed that mutations in the transcription factor TCF3 or its negative regulator ID3 occurred in approximately 70% of sporadic and immunodeficiency-related BL cases and 40% of endemic BL cases." (PMID 36001860, 2022). "The ID3 knockout mice have system immune disorder, thus, is not suitable to evaluate the function for intestinal epithelium in DSS induced colitis model." (PMID 34692671, 2021).
intrahepatic cholangiocarcinoma (4 papers, 2020 to 2025). A carcinoma that arises from the intrahepatic bile duct epithelium in any site of the intrahepatic biliary tree. "ID3 enhances intrahepatic cholangiocarcinoma (ICC) stemness by increasing β‐catenin transcriptional activity, indicating its potential as a biomarker for predicting ICC patient responses to adjuvant chemotherapy." (PMID 40078091, 2025). "Id3 could promote the stemness of intrahepatic cholangiocarcinoma by increasing the transcriptional activity of Wnt/β-catenin signaling." (PMID 32760207, 2020). "Moreover, ID3 was reported to act as a biomarker promoting the stemness of intrahepatic cholangiocarcinoma by promoting the transcriptional activity of β-catenin." (PMID 32596316, 2020).
ischemic stroke (4 papers, 2013 to 2026). A stroke disorder caused by obstruction of blood flow to the brain, due to thrombotic (local blood clot formation) or embolic (due to a blood clot or other material traveling from another site) event. "QXTLF was found to regulate the directional differentiation of LGO-induced NSCs through the Fg-mediated BMPRI/ID3 signal axis, highlighting its role in promoting the differentiation of NSCs into neurons post-ischemic stroke." (PMID 41168840, 2025). "We hypothesized that QXTLF may mitigate the extent of ischemic stroke by modulating the Fg-mediated BMPRI/ID3 signaling axis." (PMID 41168840, 2025). "We find these findings to be consistent with our bioinformatics analysis, suggesting that ID3, SLC22A4 and the NF-kB signaling pathway are very important for mediating biological processes involved in ischemic stroke." (PMID 38112574, 2023).
lung adenocarcinoma (4 papers, 2020 to 2022). A carcinoma that arises from the lung and is characterized by the presence of malignant glandular epithelial cells. "miR‐212‐5p also exerts tumour promoter function by regulating the Id3/PI3K/Akt axis in lung adenocarcinoma cells." (PMID 34697900, 2021). "Moreover, ID3 was reported to play a significant role in reversing cisplatin resistance in human lung adenocarcinoma cells by regulating the PI3K/Akt pathway." (PMID 36443709, 2022). "Moreover, a low expression level of ID3 was found in lung adenocarcinoma in the Selamat dataset, Landi dataset, Su dataset and Okayama dataset." (PMID 32003423, 2020).
medulloblastoma (4 papers, 2013 to 2024). A malignant, invasive embryonal neoplasm arising from the cerebellum. "ID3 knockdown decreased the proliferation and increased apoptosis of medulloblastoma cells and ID3 was associated with the EGFR-Akt pathway." (PMID 28283800, 2017). "This study investigated the expression of ID genes in human medulloblastoma and demonstrated that ID3 overexpression was significantly associated with tumor seeding and poor prognosis of the patients." (PMID 23768125, 2013). "High ID3 expression was associated with shorter survival of medulloblastoma patients, especially in Group 4 medulloblastomas." (PMID 23768125, 2013). "Therefore, the association of ID3 with medulloblastoma seeding may depend on these pleiotropic functions of ID3 gene." (PMID 23768125, 2013). "Knockdown of ID3 in the medulloblastoma cell line resulted in decrease of cell viability and proliferation, enhanced apoptosis, and suppressed migratory activities in vitro." (PMID 23768125, 2013). "The survival of patients with medulloblastoma in whom ID3 expression levels were assessed using RT-qPCR was analyzed." (PMID 23768125, 2013). "In vivo knockdown experiment demonstrated that ID3 not only increased migration capability, but also enhanced survival at the metastatic loci of medulloblastoma cells." (PMID 23768125, 2013). "In a seeding model of medulloblastoma, ID3 knockdown in vivo with shRNA inhibited the growth of primary tumors, prevented the development of leptomeningeal seeding, and prolonged animal survival." (PMID 23768125, 2013). "Knockdown of ID3 decreased proliferation, increased apoptosis, and suppressed the migration of D283 medulloblastoma cells in vitro." (PMID 23768125, 2013). "In vitro and in vivo studies demonstrated that the ID3 gene participated in suppression of apoptosis and the migration of medulloblastoma cells." (PMID 23768125, 2013). "In survival analysis of the patients, high ID3 expressions emerged as a poor prognostic factor, especially in patients with Group 4 medulloblastomas." (PMID 23768125, 2013). "The in vitro migration ability of D283 cells transfected with ID3-siRNA was compared with that of controls to assess the influence of ID3 gene on medulloblastoma seeding." (PMID 23768125, 2013). "Moreover, ID3 overexpression was correlated with medulloblastoma seeding and is a poor prognostic factor in medulloblastoma patients." (PMID 36443709, 2022). "Considering the general functions of ID genes in many human cancers, we postulated that ID3 may be a potential player in medulloblastoma seeding." (PMID 23768125, 2013). "Interestingly, a subgroup of medulloblastoma, Group 4 tumors showed significantly higher ID3 expression than the other subgroups." (PMID 23768125, 2013). "Interestingly, Group 4 medulloblastomas showed significantly higher ID3 expression than other subgroups." (PMID 23768125, 2013). "Knockdown of ID3 gene was performed in medulloblastoma cells in vitro." (PMID 23768125, 2013). "ID3 mRNA expression was compared in medulloblastoma cell lines, Daoy and D283." (PMID 23768125, 2013). "The risk for progression of medulloblastoma by the high expression of ID3 was 2.137 times (95% CI: = 0.684 - 6.676), which was not statistically significant after the adjustment (P = 0.192)." (PMID 23768125, 2013). "High ID3 expression was associated with medulloblastoma seeding at presentation, but not all tumors with seeding had high ID3 expression." (PMID 23768125, 2013). "Therefore, we focused on the functional role of ID3 in medulloblastoma." (PMID 23768125, 2013). "ID3 may represent the metastatic/ aggressive phenotype of a subgroup of medulloblastoma." (PMID 23768125, 2013). "Therefore, ID3 may represent the metastatic/ aggressive phenotype of Group 4 medulloblastomas that lack MYC amplification." (PMID 23768125, 2013). "The transcript level of ID3 was much higher in medulloblastomas than in normal cerebellum, and was also independent of other ID genes." (PMID 23768125, 2013).
medulloblastoma (continued). "Furthermore, in medulloblastoma tissues and cell lines examined (D283 and Daoy), basal ID4 transcript level and protein expression was negligible compared with those of ID3." (PMID 23768125, 2013). "Furthermore, ID3 transcripts were differentially elevated in seeding-positive medulloblastomas than in seeding-negative tumors." (PMID 23768125, 2013).
osteosarcoma (4 papers, 2017 to 2024). A usually aggressive malignant bone-forming mesenchymal neoplasm, predominantly affecting adolescents and young adults. "For example, it deubiquitinates and stabilizes ID1, ID2 and ID3 proteins to enhance the proliferation of osteosarcoma." (PMID 38366146, 2024). "USP1 deubiquitinates and stabilizes ID1, ID2 and ID3, resulting in the accumulation of ID proteins in osteosarcoma." (PMID 33114077, 2020).
squamous cell carcinoma (4 papers, 2015 to 2023). A carcinoma arising from squamous epithelial cells. "In squamous cell carcinoma, the inhibitor of DNA binding 3 (Id3) induced apoptosis through an Elk-1-caspase-8-dependent pathway." (PMID 30267330, 2018). "Moreover, it has also been reported that ID3 overexpression suppresses the invasion of squamous cell carcinoma cells." (PMID 37590989, 2023).
colitis (3 papers, 2015 to 2021). Inflammation of the colon. "We investigated the expression of ID3 in DSS-induced colitis mice using BMP4 recombinant protein and anti-BMP4 treatment." (PMID 34692671, 2021). "In conclusion, the present study showed that BMP4 could maintain epithelium cellular proliferation and the ISCs function through ID3 in mice with DSS-induced colitis." (PMID 34692671, 2021). "In addition, ID2 is essential for the intestinal mucosal barrier, and mice with Id2 and Id3 depletion develop colitis." (PMID 34804049, 2021). "BMP4 recombinant protein treatment could preserve Lgr5+ ISCs, colon epithelium turnover, and could even alleviate the symptoms of colitis in experimental mice by targeting ID3." (PMID 34692671, 2021). "We found that mice depleted for Id2 and Id3 expression developed colitis and αβ T-cell lymphomas." (PMID 25691468, 2015). "Numbers of granulocyte/macrophage progenitors and matured neutrophils in the peripheral organs and bone marrow were higher in Id2-deficient mice, and mice lacking Id2 and Id3 could develop colitis." (PMID 34804049, 2021). "Finally, mice depleted for Id2 and Id3 in T cells developed colitis as well as T-cell lymphoma." (PMID 25691468, 2015). "It was reported that mice lacking Id2 and Id3 could develop colitis." (PMID 34804049, 2021).
COVID-19 (3 papers, 2021 to 2025). A disease caused by infection with severe acute respiratory syndrome coronavirus 2. "CD8 T cells in both NALT and peripheral blood upregulated ID2 in acute and convalescent COVID-19, but upregulation of the long-term memory marker ID3 was significant only in convalescent patients." (PMID 39890933, 2025). "This bias was not homogeneous across all Treg-up signature genes, a ranked plot of differential expression in each donor revealing a small subset of TregUp signature genes actually down-regulated in severe COVID-19 patients (including TLR5, ID3, and FCRL1)." (PMID 34433692, 2021). "In all, 8 out of 107 HSC/MPP cells in HC and 2 out of 77 HSC/MPP cells in COVID-19 patients with mild disease expressed ID3, but not in severe cases, although PAX5 and EBF1 were not identified." (PMID 34349096, 2021).
esophageal squamous cell carcinoma (3 papers, 2020 to 2025). Esophageal squamous cell carcinoma (ESCC) is a type of esophageal carcinoma (EC) that can affect any part of the esophagus, but is usually located in the upper or middle third. "In the carcinogenesis and progression of esophageal squamous cell carcinoma, overexpression of Id3 promotes tumor expansion, migration, and invasion, while knockdown of Id3 seems to attenuate these effects, indicating that Id3 is a cancer promoter." (PMID 35599595, 2022). "In esophageal cancer, LEF1 activates the ERK/MAPK signaling pathway via the Id3/HRAS axis, thereby promoting the development and progression of esophageal squamous cell carcinoma (ESCC)." (PMID 40810004, 2025).
leukemia (3 papers, 2015 to 2022). A malignant (clonal) hematologic disorder, involving hematopoietic stem cells and characterized by the presence of primitive or atypical myeloid or lymphoid cells in the bone marrow and the blood. "ID2/ID3 protein levels in primary leukemia cells and in MEC1 cells were manipulated by transduction with siRNA reagents." (PMID 25644253, 2015). "Consistent with microarray data, the overall pattern of ID2/ID3 protein expression in relation to cell death/survival responses of primary leukemia cells was suggestive of a pro-survival function for both ID proteins." (PMID 25644253, 2015). "We deduced that the role of aberrant ID3 expression in AML survival was not directly mediated by influencing leukemia development but could affect multiple factors that lead to all-cause death in AML." (PMID 36443709, 2022).
lymph node metastasis (3 papers, 2020 to 2025). "Hypermethylation of the CpG island in the ID3 promoter leads to downregulation of ID3 in PTC cells, and this suppressed ID3 expression is strongly correlated with lymph node metastasis and poor postoperative prognosis in PTC patients." (PMID 40819127, 2025). "Additionally, we found that ESCC patients with lymph node metastases frequently had higher ID3 and CD52 expressions than ESCC patients without lymph node metastasis." (PMID 39256364, 2024).
metabolic syndrome (3 papers, 2014 to 2021). A cluster of metabolic risk factors for CARDIOVASCULAR DISEASES and TYPE 2 DIABETES MELLITUS. "An increasing body of evidence suggests that ID3 may be involved in metabolic perturbations characterized by insulin resistance, hyperglycemia, abdominal obesity, dyslipidemia, and hypertension." (PMID 28785583, 2017). "Given that metabolic perturbations are observed in endothelial cells from diseased vasculature, ID3 may mediate endothelial dysfunction often found in individuals with metabolic syndrome." (PMID 28785583, 2017). "The mechanistic implications of our findings on PCB153-induced ID3 may be with its connection to metabolic syndrome." (PMID 25090023, 2014).
neuroblastoma (3 papers, 2017 to 2024). Neuroblastoma (NB) is the most common solid, extracranial childhood tumor. "With the exception of ID2, all the other immune genes (CD8a, IL2, IL7R, IL6, ID3, and CXCR3) were also highly expressed in low-risk neuroblastoma patients further confirming the significance of these immune genes in neuroblastoma cases with favorable outcomes." (PMID 36068918, 2023).
non-small cell lung carcinoma (3 papers, 2013 to 2022). A group of at least three distinct histological types of lung cancer, including non-small cell squamous cell carcinoma, adenocarcinoma, and large cell carcinoma. "Additionally, ID1 and ID3 coexpression was correlated with a poor clinical outcome in patients with locally advanced non-small cell lung cancer treated with definitive chemoradiotherapy." (PMID 36443709, 2022). "Interestingly, ID3 expression has been involved in non-small cell lung cancer resistance to chemotherapy." (PMID 29299138, 2017).
pulmonary arterial hypertension (3 papers, 2019 to 2024). Pulmonary arterial hypertension (PAH) is a group of diseases characterized by mean pulmonary artery pressure >20 mmHg and elevated pulmonary arterial resistance leading to right heart failure. "ID3-mediated endothelial stemness further accelerates vascular changes, similarly to the mechanisms observed in pulmonary arterial hypertension." (PMID 39846697, 2024). "Given that these functions are observed in endothelial cells from diseased vasculature, ID3 may mediate pulmonary dysfunction often found in individuals with cardiopulmonary disease such as pulmonary arterial hypertension (PAH), hereditary hemorrhagic telangiectasia (HHT), and atherosclerosis." (PMID 31380118, 2019).